CD40 (CD40 molecule)
Diseases named in the same sentence as CD40 in open-access papers (continued):
Sharing a sentence is not in itself a finding about the gene and the disease.
tumor (continued). "Because of the pivotal role CD40 plays in anti-tumor immune responses, diverse strategies have been investigated to activate CD40 signaling." (PMID 39120299, 2024). "The current clinical study is limited by its small sample size and by the limited number of participants with a particular tumor type, which makes it difficult to predict which cancer type is most likely to respond to CD40-agonistic Abs." (PMID 38883779, 2024). "Several antigen presentation genes, such as Tap1 and CD74 and some regulators involved in tumor cell immunogenicity, such as Irf1, Icam1 and CD40 were also upregulated by Mi-2β knockout in vitro." (PMID 38461299, 2024). "The clinical effectiveness of CD40/CD40L anti-tumor therapy seems to be modest, displaying total response rates between 2% and 20% and partial response rates ranging from 4% to 28.6%." (PMID 39120299, 2024). "When we characterized the DC subsets during BRAFi therapy, more CD40+ activated, migratory cDC1 arrived in tumor-draining LN during BRAFi-sensitive phase, whereas percentages of CD40+ migratory CD64– cDC2 and CD64+ cDC2 were unchanged." (PMID 38631706, 2024). "In conclusion, LOAd infection increased the immunogenicity of infected tumour cells and this was potentiated by CD40 stimulation." (PMID 38494863, 2024). "Systemic administration of Flt3L, followed by a TLR3 agonist poly(I:C) or CD40 agonist, has been reported to induce the expansion and activation of tumor-residing cDC1s and enhances tumor responses to anti-PD-L1 therapy." (PMID 38926350, 2024). "In these more immunogenic tumors, the focus has been more on the activation of antigen-presenting cells via anti-CD40 mAb to help activate tumor-reactive T cells." (PMID 38731089, 2024). "Ex vivo neutrophil-activating therapy consisting of TNF, anti-CD40, and tumor-binding antibody allows rapid recruitment of neutrophils to tumors." (PMID 39769334, 2024). "A recent study found that the combination of anti-CD40 antibody and anti-IL-6 antibody for glioblastoma reversed TAMs to a tumor-killing phenotype, more effectively inhibiting tumor progression." (PMID 39403370, 2024). "Another study highlighting neutrophil-killing potential demonstrated that combination therapy involving tumor necrosis factor, CD40 agonist, and a tumor-binding antibody induced rapid mobilization and tumor infiltration of neutrophils." (PMID 38474175, 2024). "Other pharmaceutical agents, including the CCL2 inhibitor bindarit, anti-CCL2 mAb carlumab, CSF1 inhibitor GW2580, and dequalinium-14, CD40 antagonist CP-870,893, have also shown anti-tumor effects by reducing macrophage infiltration." (PMID 39146202, 2024). "The tumor necrosis factor receptor family member CD40 is critical for the immune system and induces tumor cell-specific apoptosis." (PMID 38835896, 2024). "Their study highlighted that the interaction between T-cell CD40 ligand (CD40-L) and antigen-presenting CD40 is important for T-cell activation and, furthermore, for tumor inhibition." (PMID 39061246, 2024). "Pertinently, studies elucidate that MYC inhibition reshapes the tumor immune microenvironment in OS by recruiting T lymphocytes and engaging the CD40/CD40L system." (PMID 39431237, 2024). "Conversely, the soluble form of CD40L found in serum possesses limited signaling strength when interacting with CD40 on tumor cells." (PMID 39120299, 2024). "It has been reported that CD40 activation can reverse this immunosuppressive microenvironment by facilitating the depletion of tumor stroma." (PMID 38468289, 2024). "Preclinical data suggest that the combination of a CD40 agonist and anti-PD-1/anti-PD-L1 inhibitors improves survival in mouse tumor models compared with the use of either alone." (PMID 38341519, 2024).
tumor (continued). "An agonistic anti-CD40 antibody triggered nitric oxide production in macrophages and inhibited tumor growth." (PMID 38646639, 2024). "We first compared therapy responses by re-inoculating each tumor cell line into naïve mice and administering combination therapy including gemcitabine, nab-paclitaxel, agonistic anti-CD40 Ab, anti-CTLA-4 Ab, and anti-PD-1 Ab (GAFCP)." (PMID 38378697, 2024). "Mice were treated with IL-2 in combination with agonistic antibodies to CD40, a combination that was previously demonstrated to result in marked synergistic anti-tumor effects, to determine how the thymus was effected during and after administration." (PMID 39315105, 2024). "Measurement of malondialdehyde (MDA) as a lipid peroxidation marker indicated that RSL3 administration triggered lipid oxidation production in tumor tissues, but this effect was remarkably abolished by treatment of anti-CD40 neutralizing antibody." (PMID 38594504, 2024). "Pre-clinical evidence suggests that CD40L or CD40 antibodies can be used to induce DC and macrophage-mediated cytokine release, antigen processing, tumor stroma destruction, and T-cell activation against established malignancies." (PMID 39120299, 2024). "In preclinical studies, anti-CD40 antibodies were effective in repolarizing TAMs into tumor-suppressing MΦs." (PMID 39596395, 2024). "HRS cells also modulate their interactions with CD4+ T cells by expressing surface molecules such as CD80 and CD40, which engage with immune cells to provide survival signals while simultaneously shielding the tumor from effective immune attack." (PMID 39682256, 2024). "In contrast, in the middle panel, five of five mice receiving the CAIR-minus anti-CD40 treatment became and remained tumor-free, consistent with our prior reports of greater immunotherapeutic efficacy for smaller tumors." (PMID 38731089, 2024). "Reprogramming has been another way to target microglia by changing the microglia activation state from pro-tumor to anti-tumor via Toll-like receptors (TLR) or CD40 agonists." (PMID 38238749, 2024). "Membrane-bound CD40L exhibits potent signaling capabilities upon binding to CD40 on tumor cell surfaces, enabling tumor eradication." (PMID 39120299, 2024). "Other novel drugs, including pegylated interleukin 10, colony-stimulating factor 1 receptor inhibitors, CD40 agonists, and C-X-C receptor 4 inhibitors affect the tumor microenvironment and cancer cell metabolism." (PMID 39058879, 2024). "In four different CCA mouse models, treatment with an agonistic CD40 antibody alone achieved moderate anti-tumour immunity only." (PMID 38440738, 2024). "This therapy strategy employs TNF to promote the recruitment of neutrophils to tumors, coupled with the use of CD40 agonists to activate the tumor-killing functions of neutrophils." (PMID 38523155, 2024). "For example, some researchers have constructed a tumor nano-vaccine by expressing single-chain fragment variable (scFv) of anti-CD40 antibody on the surface of cell membrane, enhancing the targeted antitumor efficiency in tumor models." (PMID 38720360, 2024). "There are studies assessing the possibility of activating neutrophils using a cocktail consisting of tumor necrosis factor, CD40 agonist, and tumor-binding antibody." (PMID 39769334, 2024). "Remarkably, in this PDAC model, two mice in the Rad + NDES CD40 group (n = 2 out of 8) achieved tumor clearance." (PMID 36658712, 2023). "The poly lactide-co-glycolide acid (PLGA)-loaded aPD-1 NPs can impact CD40+ and CD11c populations in mice tumor models, impacting dendritic cells (DC) activation, intratumoral interferon-γ (IFN-γ) production, and the tumor burden decrement." (PMID 37735656, 2023). "A higher proportion of CD38 high B cells in the blood and higher CD40 expression in tumour was prognostic of survival." (PMID 37365284, 2023).
tumor (continued). "Collectively, these data suggest that hemorrhage — through heme-activated NRF2 in macrophages of the tumor microenvironment — undermines the anti-CD40 antibody therapeutic response." (PMID 38060331, 2023). "Within these cancer types, there are conflicting reports on the prognostic significance of tumor cells expressing CD40." (PMID 36894898, 2023). "The expression levels of surface molecules such as CD11c, MHCII, CD86, and CD40 on DCs treated with mt-EVs were significantly higher than those observed in DCs treated with tumor-derived EVs (t-EVs) alone." (PMID 37946275, 2023). "While anti-PDL1 treatments are relatively well tolerated, the systemic administration of CD40 or 4-1BB agonists triggers some on-target-off-tumor toxicity which hampers their clinical use." (PMID 38053848, 2023). "A recent mouse study pinpointed that CD40 activation on cDC1 is essential for priming a CD4+ T-cell response to cell-associated antigen and help for CTL-based tumor rejection." (PMID 36639382, 2023). "Examples of positive CD40 tumor expression were found in eight out of the nine cancers surveyed, confirming previous reports that this pattern of expression is not limited to only a few cancers." (PMID 36894898, 2023). "Based on the importance of cross-priming DC in the activation of anti-tumor T cells, a recently opened trial will test the combination of Flt3 ligand, a growth factor for DC, anti-CD40 and chemotherapy in patients with metastatic TNBC68." (PMID 37620372, 2023). "In our recent work, we showed that CD40 signaling activation by monoclonal antibody rewires metabolic circuits to enhance the anti-tumorigenic polarization of TAMs and boost anti-tumor response." (PMID 37740232, 2023). "This process involved recombinant gene expression, leading to the overexpression of anti-CD40 scFv on the tumor cell surface." (PMID 37946275, 2023). "We also quantified tumor GFP fluorescence intensity after anti-CD40 treatment and found significantly higher fluorescence of the tumors grown in the conditional Keap1-KO animals." (PMID 38060331, 2023). "Agonist CD40 monoclonal antibodies (mAb) is a promising immunotherapeutic agent for cold‐to‐hot tumor immune microenvironment (TIME) conversion." (PMID 36658712, 2023). "Studies have engineered CAR T-cells to constitutively express CD40L that binds to CD40-expressing tumor cells, inducing a direct cytotoxicity effect and circumventing immune escape." (PMID 37964355, 2023). "TLR agonists and anti-CD40 antibodies (TA) can enhance the immune response by activating antigen-presenting cells (APCs) to present tumor antigens to the adaptive immune system." (PMID 37434263, 2023). "Another strategy to target TAMs in PDAC involves the application of CD40 agonists to activate their anti-tumor responses." (PMID 37771596, 2023). "The result indicated CD40 mAb administration decreased Treg population within the tumor compared to UnTx and their respective controls." (PMID 36658712, 2023). "The OS analysis in patients with initial (I and II) and advanced (III and IV) tumor stages showed a worse survival curve in the group of patients with tumors in an advanced stage and low expression of CD40 and CD40L." (PMID 37970926, 2023). "CD40 was also shown to promote tumor regression by directing macrophages to infiltrate tumors and increasing the expression of matrix metalloproteinases." (PMID 37153589, 2023). "Similar to that observed in NSCLC, CD40 expression on the tumor membrane displayed noticeable variation between cases, and a wide dynamic range of QIF scores." (PMID 36894898, 2023). "In mice receiving radiation only treatment, we observed increased the pro‐tumor M2‐like macrophages in TdLN compared to UnTx, whereas the addition of CD40 mAb treatment reduced this population." (PMID 36658712, 2023).
tumor (continued). "In a mouse model humanized both for Fc receptors and CD40, direct delivery of an Fc-engineered anti-CD40 agonistic antibody to the tumor site maintained antitumor activity, but with fewer platelet and hepatic toxicities compared to systemic administration." (PMID 38006049, 2023). "Monoclonal antibody therapy targeting CD40 acts via multiple mechanisms to stimulate anti-tumor immunity in a wide range of lymphoid and solid malignancies." (PMID 37215135, 2023). "In mouse models of PDAC, treatment with agonistic CD40 antibodies reprogramed TAMs toward anti-tumor phenotypes." (PMID 37771596, 2023). "The antibody stimulated CD40 molecules on the APC of local tumor tissue, activates tumor-specific CD8+ T cells, and is capable of eradicating local tumor tissue and distant associated tumors." (PMID 37457707, 2023). "We established an experimental model of therapy-induced hemorrhagic tumor necrosis by treating GFP-MC38 tumor–bearing mice with a single injection of the anti-CD40 agonist antibody FGK4.5 seven days after subcutaneous tumor cell injection." (PMID 38060331, 2023). "Targeting IL-6 by genetic ablation or pharmacological inhibition in combination with CD40 stimulation or PD-1/PD-L1 signaling blockade improves T-cell infiltration into tumor and enhances mouse survival." (PMID 37114049, 2023). "To examine the synergistic effect of radiation with the NDES in PDAC, we administered a single dose of 10Gy radiation locally, one day prior to CD40 mAb treatment either via IP or NDES in KPC tumor‐bearing mice." (PMID 36658712, 2023). "Here, it is shown that sustained low‐dose intratumoral delivery of CD40 mAb via the nanofluidic drug‐eluting seed (NDES) can modulate the TIME to reduce tumor burden in murine models." (PMID 36658712, 2023). "In this NSCLC cohort, 80% of the cases were positive for CD40 tumor expression according to the visual cutpoint." (PMID 36894898, 2023). "αPD-L1, CD40 agonist or the combination decreased tumor size and CD40 agonist increased spleen size in REX3 mice on day 14 posttumor, similar to our prior study." (PMID 36472588, 2023). "In tumor states, those that express higher levels of CD40/CD40L have been shown to have increased proliferation, invasion, and motility of tumor cells." (PMID 37174089, 2023). "The combination of anti-CD40/PD-1 with chemotherapy significantly impaired tumor growth and prolonged survival in advanced iCCA murine models." (PMID 37046842, 2023). "These two roles of CD40—promoting immune responses and angiogenesis—have opposing effects on the development of a tumor." (PMID 37691121, 2023). "On the other hand, in a TH2-dominated tumor microenvironment, CD40-activated macrophages fail to acquire an anti-tumor phenotype." (PMID 37693009, 2023). "One advantage of using iSRBs is that they can directly deliver the anti-CD40 (mAb) into the tumor sub-volume, which is expected to minimize systemic toxicity." (PMID 38140118, 2023). "Of note, macrophage depletion markedly compromised the anti-tumor effect of CD40 agonist, suggesting the significance of macrophages in the application of this therapy." (PMID 37771596, 2023). "In contrast, the combination of RT+ CTLA4i +anti-CD40 led to partial or complete tumor responses in 60% of the mice." (PMID 37620372, 2023). "Agonistic CD40 antibody combined with gemcitabine/nab-paclitaxel treatment changed the immunosuppressive towards a T cell-dependent tumor rejecting microenvironment in a PDAC mouse model." (PMID 37838778, 2023). "CD40 expression on the tumor membrane displayed noticeable variation between cases, as can be seen from the dynamic range of continuous QIF scores." (PMID 36894898, 2023). "Although both LMP1 and LMP2 are expressed in most EBV-associated cancers, LMP1 is the main driver of tumor progression and tumor escape from immune surveillance, because LMP1 acts as the viral equivalent of CD40." (PMID 37508413, 2023).
tumor (continued). "In murine NXS2 models, anti-CD40 treatment led to delayed tumor progression by inducing a proinflammatory M1 phenotype in macrophages and stimulating Th1 cytokine production." (PMID 38087370, 2023). "In a murine mesothelioma model, locally delivered imiquimod in combination with systemic anti-CD40 immunotherapy not only significantly enhanced the local antitumor response with 30% complete resolution, but also inhibited distal tumor growth." (PMID 38006049, 2023). "Our results indicate that B-LNP treatments induced TAMC expression of co-stimulatory factors (CD40, CD80, CD86) and enhanced tumor-associated antigen presentation, and, importantly, impaired TAMC immunosuppressive activities." (PMID 36959214, 2023). "Preclinical trials using in vivo administration of agonistic anti-CD40 antibodies resulted in effector T cell activation and tumour regression." (PMID 36980527, 2023). "CD40L is upregulated during T-cell activation, and its binding with CD40 has been demonstrated to result in upregulation of PD-L1 in tumor-infiltrating macrophages." (PMID 37465593, 2023). "Once again, CD40 expression on the tumor membrane displayed noticeable variation between cases, and a wide dynamic range of QIF scores." (PMID 36894898, 2023). "PD-L1, and CD40 that can contribute to immunologically important changes in tumor cells in vitro after electrochemotherapy with BLM, CDDP or OXA." (PMID 37243029, 2023). "Yang and colleagues demonstrated that the combination of IL-6 inhibition with CD40 stimulation reversed M2-mediated tumor immunosuppression, sensitized tumors to checkpoint blockade, and extended animal survival in two syngeneic GBM models." (PMID 37762522, 2023). "Preclinical studies demonstrate that agonistic CD40 antibodies effectively arm macrophages with cytostatic activity against tumor cells, stimulating antitumor response and slowing tumor growth." (PMID 38008741, 2023). "Combing a CD40 agonist with the chemotherapy drug gemcitabine in patients with surgically incurable pancreatic ductal adenocarcinoma led to tumor regressions in some individuals." (PMID 37426676, 2023). "For instance, a TH1-dominated tumor microenvironment can promote the ability of CD40-activated macrophages to kill malignant cells." (PMID 37693009, 2023). "CD40 agonistic antibodies can imitate the arrangement of CD40L to CD40 and initiate immune antitumor signaling in macrophages, dendritic cells, and B cells and apoptotic signaling on tumor cells." (PMID 36969193, 2023). "The mAbs target immunostimulatory receptors like 4-1BB, CR5, and CD40, then activate anti-tumor immunity that affects many cancers." (PMID 37158883, 2023). "PPARδ inactivation not only significantly reduced IL-10+ Bregs in naïve mice, but also prevented IL-10+ Breg induction by tumor and anti-CD40 engagement." (PMID 37291146, 2023). "Preclinically, mitazalimab has shown significant antitumor activity and long-term tumor-specific immunity in human CD40-transgenic mice as well as antitumor activity in immune-deficient NSG mice." (PMID 37830579, 2023). "Combining regimens, with inhibitors of TIGIT and PD-1 plus CD40 agonism, in preclinical models exhibited encouraging tumor suppression." (PMID 37727377, 2023). "In the systemic delivery group, IP CD40 alone showed a prominent tumor reduction compared to Rad + IP CD40 group." (PMID 36658712, 2023). "The bispecific antibody 4224 activates T lymphocytes to attack tumor cells, targeting CD40 and EpCAM in tumor exosomes." (PMID 36978715, 2023). "CD40 is a receptor expressed in a wide variety of cells and tissues, and the expression varies between 35-100% in established cell lines and depends on tumor histopathological type." (PMID 37970926, 2023). "In detail, CD40L-expressing CAR-Ts can interact with CD40-expressing tumor cells which results in a direct antitumor effect." (PMID 38146364, 2023).